GPRIN1 (G protein regulated inducer of neurite outgrowth 1)
Description:
May be involved in neurite outgrowth.
Synonyms: GRIN1; KIAA1893
Tractability: Antibody: UniProt places it where antibodies can reach, with medium confidence; its Gene Ontology location is reachable by antibodies, with medium confidence; the Human Protein Atlas places it where antibodies can reach. PROTAC: its protein half-life has been measured.
Gene: Protein-coding gene on chromosome 5 (176,595,802 to 176,610,177, reverse strand). Ensembl gene ENSG00000169258.
Subcellular location: Cell membrane; Cell projection, growth cone
Subcellular location (Human Protein Atlas): Plasma membrane; Vesicles
Gene Ontology:
Molecular function: protein binding; phosphoprotein binding
Biological process: neuron projection development
Cellular component: plasma membrane; growth cone
Genetic constraint (gnomAD): Loss-of-function variants: 4 observed, 1.5 expected, observed/expected ratio (o/e) 2.66. That is too few expected variants to judge how well the gene tolerates losing a copy. Missense variants: 1,141 observed, 1,059.8 expected, observed/expected ratio (o/e) 1.08, 90% interval 1.02 to 1.13. Synonymous variants: 484 observed, 451.21 expected, observed/expected ratio (o/e) 1.07, 90% interval 1 to 1.16.
Homologues: Orthologues: macaque GPRIN1 (86% identical), dog GPRIN1 (64% identical), pig GPRIN1 (63% identical), guinea pig GPRIN1 (55% identical), mouse Gprin1 (54% identical), rat Gprin1 (51% identical), tropical clawed frog gprin1 (18% identical).
Diseases named in the same sentence as GPRIN1 in open-access papers:
GPRIN1 is named in the same sentence as 15 diseases in open-access papers, as found by Europe PMC text mining. Sharing a sentence is not in itself a finding about the gene and the disease. The quoted sentences say what the papers report.
gastric cancer (4 papers, 2023 to 2026). A primary or metastatic malignant neoplasm involving the stomach. "Retraction of: Zhou W, Li P, Jin P. MiR-654-5p promotes gastric cancer progression via the GPRIN1/NF-κB pathway." (PMID 40181836, 2025). "The other authors also report a downregulation of GPRIN1 in gastric cancer (tissues and cells) and higher expression of GPRIN1 in breast cancer using the data deposited in the same database." (PMID 39329988, 2024). "Therefore, we speculate that due to the different molecular biological mechanisms of different cancers, GPRIN1 promotes the malignant behavior of tumors in lung cancer and liver cancer but plays an inhibitory role in gastric cancer." (PMID 36685007, 2023).
lung carcinoma (3 papers, 2021 to 2023). "GPRIN1 is closely related to cancer, and it can promote the proliferation and metastasis of lung cancer by promoting the epithelial-mesenchymal transition of lung cancer cells." (PMID 36685007, 2023). "GPRIN1 can promote the proliferation and migration of lung cancer." (PMID 36712848, 2022).
breast carcinoma (2 papers, 2022 to 2024). "The existing research revealed that LINC02298 might be involved in the upstream regulation of GPRIN1 and associated with the detrimental outcome of kidney renal papillary cell carcinoma and LUAD, while AP000851.2 may have an impact on stemness regulation in breast cancer." (PMID 35837104, 2022).
liver cancer (1 paper, 2023). An epithelial or non-epithelial malignant neoplasm that arises from the liver. "Our results showed that GPRIN1 was highly expressed in liver cancer tissues, and patients with high GPRIN1 expression had a worse prognosis (P=0.002)." (PMID 36685007, 2023). "Among the seven important DEGs, MAFG-DT (logFC = 2.295817), GPRIN1 (logFC = 2.444281), and MYBL2 (logFC = 3.861042) were all significantly elevated in liver cancer samples." (PMID 36685007, 2023).
lung adenocarcinoma (1 paper, 2021). A carcinoma that arises from the lung and is characterized by the presence of malignant glandular epithelial cells. "GPRIN1 proved to associate with poor prognosis and tumor immune invasion of kidney renal papillary cell carcinoma (KIRP) or lung adenocarcinoma (LUAD)." (PMID 34453499, 2021).
lymph node metastasis (1 paper, 2022). "GPRIN1 was found to be significantly high in patients with lymph node metastasis, while FCRL5 was low expressed in patients with the clinical stage, lymph node metastasis, and distant metastasis." (PMID 35903698, 2022). "Besides, high expression of GPRIN1 is highly involved in the lymph node metastasis, and FCRL5 with not only lymph node metastasis but also distant metastasis and the clinical stage of LUAD patients." (PMID 35903698, 2022).
psoriasis (1 paper, 2016). An autoimmune condition characterized by red, well-delineated plaques with silvery scales that are usually on the extensor surfaces and scalp. "We observed an increased expression of GPRIN1 and ADAM23 at the gene and protein level in PPP/PPPP as compared to psoriasis and/or normal acral skin." (PMID 27152848, 2016).
tumor (6 papers, 2017 to 2023). "ncRNA (LINC00894/MMP25‐AS1/SNHG1/LINC02298/MIR193BHG)‐mediated high expression of GPRIN1 correlates with poor prognosis and tumor immune infiltration of KIPR and LUAD." (PMID 34453499, 2021). "GPRIN1 expression was significantly correlated with tumor immune cell infiltration, immune cell biomarkers, and immune checkpoints." (PMID 34453499, 2021). "In previous screening of tumorigenesis‐related differential genes conducted by our research group, it was found that GPRIN1 was highly expressed in tumor tissues." (PMID 34453499, 2021). "In addition, the pan-cancer analysis of TGCA suggested that the expression of the G protein regulated inducer of neurite outgrowth 1 (GPRIN1) increased in 16 tumor types, included pRCC, and that it is correlated with poor prognosis." (PMID 35626699, 2022). "GPRIN1 also could affect the outcome of cancer treatment by affecting tumor immune cell infiltration and immune checkpoint expression." (PMID 34453499, 2021). "Third, the CIBERSORT algorithm was employed to calculate the proportion of various types of immune cells, and then the R packages were used for evaluating the relation between GPRIN1 expression and tumor immune cell infiltration as well as between GPRIN1 and the immune cell biomarker." (PMID 34453499, 2021). "GPRIN1 may be a novel tumor regulator, but its role and mechanism in tumors are still unclear." (PMID 34453499, 2021). "We identified four novel genes, KRTAP4-5, OR2T35, GPRIN1, and MRPL18, of unknown function in tumor progression and metastasis." (PMID 28249600, 2017). "Additional genes that had similar DNA and RNA frequency as DUSP5 and EI24 but no previous research on their potential role as a tumor suppressor were UBXN11, CAPN15, C6orf62, GPRIN1, KIAA2018, PCDHGA10, and PCGF1." (PMID 31484939, 2019).
cancer (5 papers, 2021 to 2024). A tumor composed of atypical neoplastic, often pleomorphic cells that invade other tissues. "They discovered that cancer cells regulate the expression of GPRIN1 mRNA with epigenetic mechanisms." (PMID 39329988, 2024). "The pan‐cancer analysis suggested that GPRIN1 was up‐expressed in KIRP and LUAD, and it correlated with poor prognosis." (PMID 34453499, 2021). "Pan‐cancer analysis of 33 tumors performed in this study based on the data from TCGA found that GPRIN1 was significantly overexpressed in a variety of tumors together with its correlation with prognosis." (PMID 34453499, 2021). "First, a pan‐cancer correlation analysis was conducted on the expression and prognosis of GPRIN1 based on the data downloaded from The Cancer Genome Atlas (TCGA) database." (PMID 34453499, 2021). "As shown in the heatmaps, the hsa_circ_0001495, miR-125b-5p, and GPM6A were down-regulated in cancer tissues compared to their paired para-carcinomal tissues of HCC, whereas hsa_circ_0000688, miR-106b-5p, and four mRNAs (UNKL, GPRIN1, SMYD5, AURKB) were up-regulated." (PMID 35002514, 2022). "Moreover, GPRIN1 is not among the proteins broadly overexpressed in various cancers." (PMID 39329988, 2024).
neurological diseases (1 paper, 2024). "However, molecular effects through the associated competitive endogenous (ceRNA) of miR-140-3p-GPRIN1 axis of LINC02298, or through cytochrome c oxidase subunit 6C (COX6C) function, as found in other neurological diseases, may still be possible." (PMID 39338942, 2024).
GPRIN1 also shares sentences with these, for which no sentence is quoted: cognitive deficits (1 paper); gallbladder cancer (1); neurodevelopmental disorder (1); non-small cell lung carcinoma (1); pancreatic adenocarcinoma (1).